DMD (dystrophin)
Diseases named in the same sentence as DMD in open-access papers (continued):
Sharing a sentence is not in itself a finding about the gene and the disease.
Duchenne muscular dystrophy (continued). "Duchenne muscular dystrophy is a highly complex multi-system disease caused by primary abnormalities in the membrane cytoskeletal protein dystrophin." (PMID 30386187, 2018). "An out-of-frame mutation of the dystrophin pre-mRNA leads to the development of Duchenne muscular dystrophy (DMD)." (PMID 29622040, 2018). "Dystrophin-deficiency results from mutations in the DMD gene and can manifest as Duchenne muscular dystrophy (DMD)." (PMID 30410044, 2018). "Duchenne muscular dystrophy (DMD) is an X-linked recessive neuromuscular disease caused by mutations in the dystrophin gene." (PMID 30406066, 2018). "Duchenne muscular dystrophy (DMD) is a lethal disease caused by point mutations in the dystrophin gene due to stop codon in exon 23 out of 79 exons." (PMID 30607328, 2018). "Duchenne muscular dystrophy (DMD) is caused by mutations in the dystrophin gene resulting in progressive muscle wasting and weakness." (PMID 28587652, 2017). "Duchenne muscular dystrophy is a progressive degenerative disease of muscles caused by mutations in the dystrophin gene." (PMID 28742067, 2017). "Duchenne muscular dystrophy is characterized by striking temporal differential involvement of cardiac and skeletal muscles, despite shared dystrophin protein deficiency and similar physiological functions in the two muscle types." (PMID 28390424, 2017). "Duchenne muscular dystrophy (DMD) is an X-linked recessive muscle-wasting disease caused by a mutation in the DMD gene." (PMID 28344651, 2017). "Mutations in dystrophin are associated with a spectrum of clinical phenotypes, grouped as “dystrophinopathies” including Duchenne muscular dystrophy (DMD), Becker muscular dystrophy (BMD), and X-linked dilated cardiomyopathy (XLDCM)." (PMID 28575024, 2017). "Duchenne muscular dystrophy (DMD) is an X-linked genetic disorder resulting from mutations in the dystrophin gene." (PMID 28785010, 2017). "The DMD gene encoding dystrophin is mutated in Duchenne muscular dystrophy, a fatal progressive muscle wasting disease." (PMID 28546788, 2017). "Duchenne muscular dystrophy arises from the loss of dystrophin and is characterized by calcium dysregulation, muscular atrophy, and metabolic dysfunction." (PMID 27921261, 2017). "Dystrophin deficiency caused by mutations in the DMD gene is a fundamental defect in Duchenne muscular dystrophy (DMD), one of the most common inherited muscular diseases." (PMID 28546788, 2017). "Duchenne muscular dystrophy is a hereditary X-linked neuromuscular disorder caused by mutations in the dystrophin gene, with a prevalence of 1:5,000 male newborns." (PMID 29123500, 2017). "Duchenne muscular dystrophy (DMD) is the most common disease in children caused by mutations in the DMD gene, and DMD and Becker muscular dystrophy (BMD) are collectively called dystrophinopathies." (PMID 28859693, 2017). "Duchenne muscular dystrophy (DMD) is an X-linked recessive disorder caused by dystrophin gene mutations." (PMID 28152980, 2017). "Dystrophin-deficient dogs are by far the best available large animal models for Duchenne muscular dystrophy (DMD), the most common lethal childhood muscle degenerative disease." (PMID 28339469, 2017). "Duchenne muscular dystrophy (DMD), which involves a progressive deterioration of muscle function, is caused by frame-shifting deletions or nonsense mutations in the DMD gene." (PMID 27754374, 2016). "Since alterations in dystrophin expression are primarily involved in Duchenne muscular dystrophy, Becker muscular dystrophy and X-linked dilated cardiomyopathy, mass spectrometry-based proteomics has been mostly applied in comparative biomedical studies." (PMID 26793286, 2016). "Duchenne muscular dystrophy (DMD) is an X-linked muscle disease caused by mutations in the dystrophin gene." (PMID 27213537, 2016).
Duchenne muscular dystrophy (continued). "Recently, loss of dystrophin expression in SCs in Duchenne muscular dystrophy was shown to reduce the available pool of SCs for repair, contributing to the pathogenesis of this disease." (PMID 27923399, 2016). "Duchenne muscular dystrophy (DMD) is a recessive lethal inherited muscular dystrophy caused by mutations in the gene encoding dystrophin, a protein required for muscle fibre integrity." (PMID 27594988, 2016). "Lastly, the NOTCH ligand Jagged1 rescues the Duchenne muscular dystrophy phenotype in zebrafish embryos and is upregulated in mildly affected dystrophin-deficient dogs." (PMID 27554485, 2016). "Duchenne muscular dystrophy is a severe and currently incurable progressive neuromuscular condition, caused by mutations in the DMD gene that result in the inability to produce dystrophin." (PMID 26974331, 2016). "Duchenne muscular dystrophy (DMD) is a genetic disorder caused by mutations in the dystrophin-encoding DMD gene." (PMID 27215286, 2016). "Duchenne muscular dystrophy (DMD) is an X-linked genetic disorder caused by mutations in the gene that encodes the cytoskeletal protein dystrophin." (PMID 27241590, 2016). "Duchenne muscular dystrophy (DMD) is caused by genetic deficiency of dystrophin and characterized by massive structural and functional changes of skeletal muscle tissue, leading to terminal muscle failure." (PMID 27634466, 2016). "Duchenne muscular dystrophy is an X-chromosome-linked genetic disease, which is characterized by the mutation and loss of dystrophin expression." (PMID 28979820, 2016). "Duchenne muscular dystrophy (DMD) is an X-linked genetic disease caused by mutations in the dystrophin gene." (PMID 26251044, 2015). "Duchenne Muscular dystrophy is caused by Dystrophin gene mutations many of which induce frameshifting exon skipping events." (PMID 25985083, 2015). "Duchenne muscular dystrophy (DMD) is a monogenetic X-chromosome linked recessive disorder with mutations of the dystrophin gene, resulting in a deficient and lowered dystrophin protein." (PMID 25973604, 2015). "Duchenne muscular dystrophy is a fatal neuromuscular disease affecting about 1 in 5000 boys, which is caused by mutations in the gene coding for the dystrophin protein." (PMID 26504514, 2015). "Duchenne muscular dystrophy (DMD) occurs due to genetic mutations that lead to absence or decrease of dystrophin protein generating progressive muscle degeneration." (PMID 26074983, 2015). "The clinical and histhopathologic findings were similar to the severe Duchenne muscular dystrophy in Golden Retrievers with a genetic defect in the X-linked DMD gene encoding dystrophin." (PMID 26438297, 2015). "Dystrophin of the dystrophin-glycoprotein complex connects the actin cytoskeleton to basement membranes and loss of dystrophin results in Duchenne muscular dystrophy." (PMID 26345322, 2015). "Dystrophin was first identified by Hoffman and colleagues as the protein missing from X-linked Duchenne muscular dystrophy (DMD) patients in 1987." (PMID 26230713, 2015). "Duchenne muscular dystrophy (DMD) is a genetic disorder that occurs with a frequency of approximately 1 in every 3500 live male births resulting from mutations in the dystrophin gene, located on the short arm of the X chromosome." (PMID 26248188, 2015). "Duchenne muscular dystrophy (DMD) is a severe muscle-degenerative disease caused by a mutation in the dystrophin gene." (PMID 25434822, 2015). "Duchenne Muscular Dystrophy (DMD) is the most frequent genetic disorder which is caused by mutation in X linked dystrophin gene." (PMID 26230628, 2015). "Progressive diseases of skeletal and cardiac muscles with primary abnormalities in the dystrophin gene include Duchenne muscular dystrophy, Becker muscular dystrophy, and X-linked dilated cardiomyopathy." (PMID 28248273, 2015). "Duchenne muscular dystrophy (DMD) is a severe muscle wasting disorder typically caused by frame-shifting mutations in the DMD gene." (PMID 26623937, 2015).
Duchenne muscular dystrophy (continued). "There has been a case report of Duchenne muscular dystrophy caused by homozygosity for a deletion of exon 50 of the dystrophin gene in a female with natural UPD(X)." (PMID 27462421, 2015). "Duchenne muscular dystrophy (DMD) is caused by mutations in the dystrophin gene, which consists of 79 exons, located on the X chromosome, making it a potential candidate for gene therapy." (PMID 26137216, 2015). "This again can be seen with the DMD gene: variants that lead to a complete loss of function cause the severe Duchenne muscular dystrophy, whereas variants that only partially affect dystrophin function result in the milder Becker muscular dystrophy." (PMID 26438297, 2015). "Duchenne muscular dystrophy (DMD) is a severe muscular degenerative disease caused by loss-of-function mutations in the dystrophin gene located on the X chromosome." (PMID 25434822, 2015). "A mutation to Dystrophin gene that encodes dystrophin causes Duchenne muscular dystrophy, and has been suggested as being a major component of the sub-sarcolemmal cytoskeleton involved in maintaining the integrity of the myofiber plasma membrane." (PMID 25942471, 2015). "Duchenne muscular dystrophy, the most common type of MD, is due to a mutation in the dystrophin gene and has been modeled by adenoviral expression of MyoD1 and by inducible lentiviral Pax3 overexpression." (PMID 26239126, 2015). "Duchenne muscular dystrophy is a lethal X‐linked disorder caused by mutations in the dystrophin gene." (PMID 26140505, 2015). "Duchenne muscular dystrophy (DMD) is an X-linked genetic disease caused by mutations in the dystrophin gene, leading to progressive lethal muscle degeneration, chronic inflammatory response, and fibrosis." (PMID 25999854, 2015). "Using the TALEN and CRISPR-Cas9 systems, Hotta and colleagues restored the disease-causing mutation of the dystrophin gene by exon skipping, frameshift, and exon knockin approaches in Duchenne muscular dystrophy patient-derived iPSCs." (PMID 25434822, 2015). "It is well documented that in Duchenne muscular dystrophy and corresponding animal models, expression of the mutated dystrophin gene is down-regulated." (PMID 26631063, 2015). "For example, utrophin is well known to compensate for the loss of dystrophin in mice and results in a much milder phenotype than in human Duchenne muscular dystrophy." (PMID 26693275, 2015). "Duchenne muscular dystrophy (DMD) is an X-linked recessive disorder (one of the dystrophinopathies) that is due to mutations in the dystrophin gene, encoding the dystrophin protein." (PMID 26124831, 2015). "The pathological status of the mdx mouse model of Duchenne muscular dystrophy is based on a point mutation in exon 23 of the dystrophin gene, resulting in a truncated protein product that is quickly degraded in dystrophic fibres." (PMID 24772416, 2014). "In the most common form, Duchenne muscular dystrophy (DMD) mutations in the dystrophin gene lead to the loss of protection from contraction-induced injury." (PMID 25313366, 2014). "Characterization of the sapje zebrafish, a model of Duchenne muscular dystrophy, has demonstrated that dystrophin loss is associated with destabilization of the myocyte-MTJ attachment leading to detachment and cell death." (PMID 24478725, 2014). "Duchenne muscular dystrophy (DMD) is caused by mutations in dystrophin gene leading to progressive muscle wasting." (PMID 25018733, 2014). "Cardiorespiratory complications are frequent symptoms of Duchenne muscular dystrophy, a neuromuscular disorder caused by primary abnormalities in the dystrophin gene." (PMID 24772416, 2014). "Duchenne muscular dystrophy (DMD) is caused by mutations in the dystrophin gene and patients suffer from decrease of muscle tissue." (PMID 24575400, 2014). "Duchenne muscular dystrophy is a severe muscle-wasting disease caused by mutations in the dystrophin gene that ablate functional protein expression." (PMID 24643206, 2014).
Duchenne muscular dystrophy (continued). "Approximately 13% of boys with Duchenne muscular dystrophy (DMD) have a nonsense mutation in the dystrophin gene, resulting in a premature stop codon in the corresponding mRNA and failure to generate a functional protein." (PMID 24349052, 2013). "AON-mediated exon skipping has enabled the successful reframing of the mutated dystrophin mRNA and the restoration of dystrophin protein synthesis in skeletal muscle of Duchenne muscular dystrophy (DMD) patients." (PMID 23861958, 2013). "Duchenne muscular Dystrophy (DMD) is an inherited disease caused by mutations in the dystrophin gene that disrupt the open reading frame, while in frame mutations result in Becker muscular dystrophy (BMD)." (PMID 24282529, 2013). "DMD nonsense and frameshift mutations lead to severe Duchenne muscular dystrophy while in-frame mutations lead to milder Becker muscular dystrophy." (PMID 23536893, 2013). "Duchenne muscular dystrophy (DMD) is an X-linked genetic disorder resulting in a defect in the muscle membrane protein called dystrophin." (PMID 23509749, 2013). "The progressive muscle wasting condition Duchenne muscular dystrophy (DMD) is caused by loss-of-function mutations in the DMD gene, which encodes the structural and signalling protein dystrophin." (PMID 23945935, 2013). "Hypertrophy of dystrophin-deficient muscles has been observed in some models of Duchenne muscular dystrophy, including the mdx mouse." (PMID 23828267, 2013). "Even though the DMD gene has been identified as the mutated locus causal for Duchenne muscular dystrophy, multiple other loci are suspected to be involved in the phenotypic variability in DMD patients, perhaps via epistatic interactions." (PMID 24403852, 2013). "Duchenne muscular dystrophy (DMD) is caused by null mutations in the dystrophin gene that encodes a membrane-associated structural protein." (PMID 23977226, 2013). "Duchenne muscular dystrophy (DMD) is an X-linked lethal muscle disease caused by mutations in the dystrophin gene." (PMID 23544107, 2013). "Duchenne muscular dystrophy caused by a mutation in the X-linked dystrophin gene induces metabolic and structural disorders in the brain." (PMID 24244600, 2013). "Manipulation of dystrophin pre-mRNA processing offers the potential to overcome mutations in the dystrophin gene that would otherwise lead to Duchenne muscular dystrophy." (PMID 22182525, 2012). "Mutations in dystrophin give rise to dystrophinopathies, a term that includes Duchenne muscular dystrophy (DMD), Becker muscular dystrophy (BMD) and X-linked dilated cardiomyopathy (XLDCM)." (PMID 22937058, 2012). "Duchenne muscular dystrophy is an X-linked recessive muscular disorder, caused by mutations in the dystrophin gene (DMD)." (PMID 22319435, 2012). "Becker muscular dystrophy (BMD) is a dystrophinopathy caused by mutations in DMD gene that shows a milder disease course as compared to Duchenne muscular dystrophy (DMD)." (PMID 23251671, 2012). "Mutations in the gene encoding the cytoskeletal protein dystrophin cause the X-linked fatal muscle wasting disease Duchenne muscular dystrophy (DMD)." (PMID 23139842, 2012). "Disruption of the sarcolemma-associated dystrophin-glycoprotein complex underlies multiple forms of muscular dystrophy, including Duchenne muscular dystrophy and sarcoglycanopathies." (PMID 22640601, 2012). "Duchenne muscular dystrophy is a lethal genetic disease of childhood caused by primary abnormalities in the gene coding for the membrane cytoskeletal protein dystrophin." (PMID 22614334, 2012). "DMD encodes actin-binding cytoskeletal structure molecule, which has been mostly studied in patients with Duchenne’s muscular dystrophy." (PMID 23110343, 2012). "Duchenne muscular dystrophy, a fatal muscle-wasting disease, is characterized by dystrophin deficiency caused by mutations in the dystrophin gene." (PMID 22462762, 2012).
Duchenne muscular dystrophy (continued). "Duchenne muscular dystrophy (DMD) is a degenerating striated muscle disease caused by the absence of the dystrophin protein." (PMID 21586145, 2011). "For example, dystrophin is associated with the cytoskeleton and its absence causes Duchenne muscular dystrophy (DMD), while emerin is located in the nuclear membrane and its deficiency underlies X-linked Emery-Dreifuss muscular dystrophy (X-EDMD)." (PMID 21364987, 2011). "Lack or vast reduction of dystrophin causes severe Duchenne muscular dystrophy (DMD) in humans and myopathy in corresponding mouse models, such as the mdx or mdx-3Cv mouse." (PMID 21533183, 2011). "Duchenne muscular dystrophy is a degenerative muscle disease caused by a mutation of the gene encoding dystrophin, a protein that anchors the myofiber cytoskeleton to the basal lamina, resulting in muscle fiber necrosis and progressive weakness." (PMID 22195027, 2011). "Duchenne muscular dystrophy (DMD) is an X-linked recessive disease characterized by mutations in the gene encoding the membrane protein dystrophin." (PMID 22140444, 2011). "The murine model of Duchenne muscular dystrophy (mdx mutant mouse) bears a point mutation in the gene coding for dystrophin, which causes the premature termination of the polypeptide chain during translation." (PMID 22066028, 2011). "A major cause of pediatric HF, Duchenne muscular dystrophy (DMD) is an X-linked recessive disorder characterized by disruption of the dystrophin protein." (PMID 21288342, 2011). "Duchenne muscular dystrophy (DMD) is a lethal muscle wasting disease caused by mutations in the DMD gene which prevents the translation of a functional dystrophin protein." (PMID 22318674, 2011). "Mutations in dystrophin can lead to Duchenne muscular dystrophy or the more mild form of the disease, Becker muscular dystrophy." (PMID 20502633, 2010). "Genetic mutations affecting the expression of the dystrophin gene, as with Duchenne muscular dystrophy (DMD), impair cellular ability to resist muscle contractile forces and result in striated muscle cell death and fibrosis of the investing connective tissue." (PMID 20815903, 2010). "Duchenne's muscular dystrophy (DMD) is a severe progressive myopathy caused by mutations in the DMD gene leading to a deficiency of the dystrophin protein." (PMID 20975992, 2010). "Dystrophin, in particular, appears especially susceptible to the evolutionary modification in protein expression, as dimensionally expressed in terms either of Duchenne muscular dystrophy or else as Becker's muscular dystrophy." (PMID 21151513, 2010). "Systemic myostatin inhibition led to increased skeletal muscle mass and strength in control C57 Bl/6 mice and in the dystrophin-deficient mdx model of Duchenne muscular dystrophy." (PMID 20161803, 2010). "We studied the effects of chronic administration of Tβ4 on the skeletal and cardiac muscle of dystrophin deficient mdx mice, the mouse model of Duchenne muscular dystrophy." (PMID 20126456, 2010). "Duchenne muscular dystrophy (DMD) is a prevalent lethal muscle disease caused by dystrophin gene mutation." (PMID 21187970, 2010). "Mutations in dystrophin can lead to a severe muscle wasting disease called Duchenne muscular dystrophy (DMD) in young boys." (PMID 20502633, 2010). "In Duchenne muscular dystrophy the mutation is in dystrophin, a protein that is involved in the formation of the dystrophin–glycoprotein complex." (PMID 19478831, 2009). "dys-1 encodes an orthologue of the human DMD, which when mutated leads to Duchenne muscular dystrophy, a severe recessive x-linked form of muscular dystrophy that is characterized by rapid progession of muscle degeneration." (PMID 19503817, 2009). "Mutations that disrupt the open reading frame and prevent full translation of DMD, the gene that encodes dystrophin, underlie the fatal X-linked disease Duchenne muscular dystrophy." (PMID 19713152, 2009).